ENSG00000253656 (novel transcript)
Gene: Long non-coding RNA gene on chromosome 8 (130,558,288 to 130,655,712, reverse strand). Ensembl gene ENSG00000253656.
Gene Ontology:
Biological process: formation of quadruple SL/U4/U5/U6 snRNP; spliceosomal tri-snRNP complex assembly
Cellular component: U4/U6 x U5 tri-snRNP complex; U5 snRNP